TOX (thymocyte selection associated high mobility group box)
Diseases named in the same sentence as TOX in open-access papers (continued):
Sharing a sentence is not in itself a finding about the gene and the disease.
cutaneous T-cell lymphoma (8 papers, 2016 to 2021). "TOX is a diagnostic marker for cutaneous T-cell lymphomas (CTCL) and is overexpressed in affected CD4+ cells Retinoids have been successfully used in the therapy of CTLC for over 30 years and are still being used in T-cell lymphoma therapy." (PMID 33653267, 2021). "Concerning the potential diagnostic clinical use of TOX immunostaining for cutaneous T-cell lymphomas, the presence of TOX-expression in reactive T cells present in inflammatory cutaneous disorders also prevents its diagnostic use for the recognition of MF." (PMID 32106280, 2020). "In the past few years, TOX [thymocyte selection-associated high-mobility group (HMG) box] has been described as a potential new diagnostic marker for cutaneous T-cell lymphoma (CTCL)." (PMID 27180090, 2016). "It has been reported that TOX is able to regulate cell cycle in primary Sézary cells and cutaneous T cell lymphoma, whereas TOX knockdown leads to cell cycle arrest and secondary cell death." (PMID 31676945, 2020). "In recent years, TOX has been characterized as a promising drug target in cutaneous T cell lymphoma." (PMID 31554191, 2019). "Notably, overexpression of TOX was found to have adverse prognostic implications in cutaneous T-cell lymphomas (CTCL), where it correlated with disease progression and mortality." (PMID 32106280, 2020).
lymphoma (8 papers, 2015 to 2025). A malignant (clonal) proliferation of B- lymphocytes or T- lymphocytes which involves the lymph nodes, bone marrow and/or extranodal sites. "Further support for the possible diagnostic relevance of TOX expression is provided by recent reports showing that the TOX gene family is aberrantly expressed or mutated in diverse types of lymphoma and other cancer types." (PMID 32106280, 2020). "While the cancer-related roles of TOX are still not fully understood, recent studies have shown that TOX expression or mutations are deregulated in several diseases, particularly in malignancies like lung, breast, and gastric cancers, as well as lymphomas and leukemia." (PMID 40303305, 2025). "To further investigate the role of TOX and its potential diagnostic value in lymphomas here we have evaluated the labeling of a new anti-TOX monoclonal antibody (mAb) that works on paraffin-embedded tissues from a large series of normal tissues and B- and T-cell neoplasms." (PMID 32106280, 2020). "The chronic stimulation by lymphoma results in T cell exhaustion driven by transcription factors such as TOX, EOMES, BATF, and IRF4, which is further affected by the immunosuppressive microenvironment and more lines of therapy." (PMID 40248244, 2025). "There is extensive evidence that abnormal TOX expression leads to lymphoma development, especially T-lymphoma." (PMID 36969216, 2023). "Based on the previous finding of TOX expression concurrent with that of PD-1 and Tim-3 in T cells from patients with lymphoma, we analyzed the correlation of the gene expression level of the TOX genes and IC genes in AML patients." (PMID 34692519, 2021). "Overall TOX expression was detected in 65% of FL and showed reduced frequency of expression in low grade 1 lymphomas (grade 1, 43%; grade 2, 73%; grade 3A, 73%; grade 3B, 67%)." (PMID 32106280, 2020). "The 63kDa and 57kDa TOX proteins were observed in multiple lymphoma cell lines including DLBCL (DB, SUDHL4 and SUDHL10 (weak positivity)), BL (RAMOS and RAJI), FL (WSU-NHL), CTCL (HH and MYLA), TCL (YT) and T-ALL (SUP-T1 and MOLT4) cell lines." (PMID 32106280, 2020). "While there are several reports describing the role played by TOX in development of the immune system, little is known about its expression and function in lymphomas." (PMID 32106280, 2020). "NFIL3 has been shown to directly bind to the TOX promoter in a mouse lymphoma cell line and ectopic expression of TOX restored ILCs in the absence of NFIL3, though with low efficiency." (PMID 26556952, 2015). "In malignant T-cell lymphomas, TOX is highly expressed in MF, T-lymphoblastic lymphoma, angioimmunoblastic T-cell lymphoma, and in a lower level in peripheral T-cell lymphoma and other lymphomas." (PMID 35054387, 2022). "Interestingly, the expression of TOX appears to be different in different types of lymphoma." (PMID 33743809, 2021).
hepatocellular carcinoma (7 papers, 2020 to 2025). A malignant tumor that arises from hepatocytes. "TOX expression is predictive of T cell exhaustion and unfavorable outcome in hepatocellular carcinoma animal models and clinical samples, in line with the paradigm of TOX-mediated, TCR-dependent T cell dysfunction." (PMID 34032638, 2021). "However, after the development of hepatocellular carcinoma, T cell exhaustion was inevitable, and it was marked by the exhaustion of the signature transcription factor TOX." (PMID 38032223, 2024). "TOX-deficient TST cells lead to decreased expression of IRs and regain the ability to proliferate, while TOX-deficient TST cells still exhibit decreased cytokine production and cytotoxicity in the murine model of hepatocellular carcinoma." (PMID 36969216, 2023). "In hepatocellular carcinoma (HCC), TOX facilitates PD-1 endocytic recycling, thereby resulting in sustained high levels of PD1 expression." (PMID 40093905, 2025). "In a mouse model of hepatocellular carcinoma (HCC), TOX was upregulated in exhausted CD8+ T cells, impairing their anti-tumor function." (PMID 32117960, 2020). "When stably expressed, TOX drives Ag-specific T cell exhaustion in mouse models of chronic lymphocytic choriomeningitis virus (LCMV) infection, transplantable B16 melanoma, and inducible hepatocellular carcinoma." (PMID 34032638, 2021). "Finally, high expression of TOX in peripheral CD8+ T cells correlated with poorer anti-PD-1 therapeutic responses and prognosis in hepatocellular carcinoma." (PMID 32106280, 2020).
lung adenocarcinoma (6 papers, 2020 to 2024). A carcinoma that arises from the lung and is characterized by the presence of malignant glandular epithelial cells. "In this study, we identified TOX is a prognosis‐related biomarker for multiple cancer types especially lung adenocarcinoma and correlate with immune infiltration levels in most of immune cells and functional T cells." (PMID 32700817, 2020). "In addition, TOX was also found to correlate with prognosis, immune infiltration and T cells exhaustion in lung adenocarcinoma." (PMID 36434543, 2022). "Our findings suggested that detecting expression level of TOX may help to predict prognosis and regulating TOX expression in exhausted T cells may provide a potential strategy in maximizing immunotherapy efficacy for lung adenocarcinoma patients." (PMID 32700817, 2020). "Similarly, the survival analysis of TCGA NSCLC cohort (LUAD, lung adenocarcinoma, and LUSC, lung squamous cell carcinoma) revealed that a high overall survival rate was associated with low TOX expression level in the T cells (P = 0.0393, log-rank test)." (PMID 32111241, 2020). "Moreover, single‐cell RNA‐seq for T cells in lung adenocarcinoma was acquired and analyzed in an open database to further explore the correlations between TOX expression and different T cells populations." (PMID 32700817, 2020). "Furthermore, it was showed that increased TOX expression positively correlated with high immune infiltration levels in most of the immune cell and functional T cells including exhausted T cell in lung adenocarcinoma tissues." (PMID 36434543, 2022).
lung cancer (6 papers, 2012 to 2025). A malignant neoplasm involving the lung. "Given AHR's previously demonstrated tumor-suppressive role in lung cancer 17, TOX upregulation may contribute to As3+-induced malignancy." (PMID 40303305, 2025). "Flow cytometric analysis of mouse TI CD8+ cells isolated from various cancer models, including MC38 colon cancer, CT26 colon cancer, TC-1 lung cancer, and LLC1 lung cancer, revealed a similar correlation between TOX expression and TI CD8+ T cell exhaustion severity." (PMID 32111241, 2020). "To explore the role of TOX in carcinogenesis, we analyzed the correlation between AHR and TOX expression using RNA-seq data from human lung cancer, which revealed a negative correlation between AHR and TOX." (PMID 40303305, 2025).
acute myeloid leukemia (5 papers, 2021 to 2025). Acute myeloid leukemia (AML) is a group of neoplasms arising from precursor cells committed to the myeloid cell-line differentiation. "They demonstrated that targeting TOX gene in acute myeloid leukemia patients could be a meaningful and precise treatment strategy." (PMID 39758401, 2025). "TOX might be considered a potential target for reversing T cell exhaustion in acute myeloid leukemia." (PMID 39758401, 2025). "In addition, the simultaneous increase of TOX, along with CD244, PD-1, and Tim-3, in T cells was found to correlate with T cell exhaustion in acute myeloid leukemia." (PMID 39758401, 2025).
central nervous system lymphomas (5 papers, 2016 to 2024). "Interestingly TOX mutations were also found in primary central nervous system lymphoma (PCNSL), another large B-cell lymphoma type with an ABC phenotype, where they have been found to be associated with shorter overall survival." (PMID 32106280, 2020). "Moreover, it was found in primary central nervous system lymphomas (PCNSL) that approximately 32% of patients have TOX deletion." (PMID 33743809, 2021). "Additional mechanisms that could explain some variability in the expression of the TOX protein might be genetic alterations including copy number variation such as amplification/deletion or translocations involving TOX, as observed in DLBCL and primary central nervous system lymphoma." (PMID 32106280, 2020).
mycosis fungoides (5 papers, 2014 to 2022). Classical mycosis fungoides is the most common type of mycosis fungoides (MF), a form of cutaneous T-cell lymphoma, and is characterized by slow progression from patches to more infiltrated plaques and eventually to tumors. "In T cell lymphomas, TOX is highly expressed in mycosis fungoides (MF), precursor T lymphoblastic lymphoma, and angioimmunoblastic T-cell lymphoma (AITL), but it is expressed at a low level in peripheral T-cell lymphoma cell lymphoma (PTCL) and anaplastic large cell lymphoma (ALCL)." (PMID 33743809, 2021).
myeloma (5 papers, 2020 to 2025). "The proportion of the TOX+ Treg subgroup is increased in patients with non-Hodgkin’s lymphoma, multiple myeloma (MM), or de novo AML, and this phenomenon results in Treg activation instead of Treg exaustion." (PMID 36969216, 2023). "Through co‐culture experiments with activated T cells, we found that overexpression of SEI1 in myeloma cells can significantly inhibit the killing efficiency of activated T cells and promote the expression of T‐cell exhaustion markers (TOX, TIGIT, and TIM3)." (PMID 40135791, 2025). "A finding that could suggest a possible role of truncating mutations in the TOX gene as regulators of the plasma cell programme, as indicated by the absence of TOX expression in plasma cells and myelomas and the inactivation of this programme in ABC-DLBCL." (PMID 32106280, 2020). "Conversely, the top-200 genes that negatively correlated with TOX exhibited significant overlap with post-GC B-cell signatures, including down-regulated signatures in FL (compared to reactive lymph node or NMZL either), IRF4 programme in myeloma and plasma cells and MYD88 up-regulated transcriptome." (PMID 32106280, 2020).
Sézary syndrome (5 papers, 2019 to 2025). "TOX was shown to be highly expressed in both MF and Sézary syndrome, and its expression is related to poor patient prognosis." (PMID 35241665, 2022). "We examined regulation of RUNX3 by TOX in malignant CD4+ cells derived from PMBCs of Sézary syndrome patients." (PMID 31139323, 2019). "Recently, gene expression profiling and additional immunohistochemical studies have suggested that TOX might represent a potential marker for the histological diagnosis of CTCL, being aberrantly expressed in CD4 neoplastic T cells in MF and Sezary syndrome." (PMID 32106280, 2020).
B-cell lymphomas (4 papers, 2016 to 2021). "Altered TOX function, either via physiological changes in protein expression or resulting from truncating somatic mutations, may also play a role in B-cell lymphoma pathogenesis." (PMID 32106280, 2020). "In B-cell lymphoma, TOX is overexpressed in precursor B lymphoblastic lymphoma (B-LBL), diffuse large B cell lymphoma (DLBCL), follicular lymphoma (FL), and a small proportion of Burkitt lymphoma (BL) patients." (PMID 33743809, 2021). "In a following analysis of the data obtained from this study, we found that TOX was expressed in multiple B-cell lymphoma types including a high proportion of large B-cell lymphoma cases." (PMID 32106280, 2020). "GEP analysis revealed significant overexpression in FL of TOX mRNA across low-grade B-cell lymphoma samples and reactive lymphoid tissues." (PMID 32106280, 2020). "In B-cell lymphomas, high TOX protein expression was found in precursor B-LBL (66%), DLBCL (72%) and FL (65%) and in a low percentage of BL (33%)." (PMID 32106280, 2020). "TOX was also expressed in reactive GC B cells and in primary cutaneous B-cell lymphomas (BCL6+ primary cutaneous large B-cell lymphoma leg-type and secondary cutaneous DLBCL), indicating that this gene may play a role in B-cell lymphoma pathogenesis." (PMID 32106280, 2020). "Our recent study also showed that TOX is highly co-expressed with PD-1, Tim-3, and CD244 in CD3+ T cells, particularly in CD3 + CD8+ cells in patients with B cell non-Hodgkin’s lymphoma (B-NHL)." (PMID 33743809, 2021). "TOX gene expression in FL was then further analyzed in comparison to other B-cell lymphomas (MALT, SMZL, MCL and CLL) and reactive lymphoid tissue (lymph node and spleen), where we found significant TOX overexpression in FL for all tests (fold change >2, FDR <0.05." (PMID 32106280, 2020). "In our previous study, we found higher TOX expression concurrent with PD-1, Tim-3, or CD244 in T cells from patients with B cell non-Hodgkin’s lymphoma (B-NHL), which suggested that TOX may be involved in inducing CD8+ T cell exhaustion by co-regulation with immune checkpoint proteins." (PMID 34692519, 2021).
COVID-19 (4 papers, 2021 to 2025). A disease caused by infection with severe acute respiratory syndrome coronavirus 2. "In various diseases, including COVID-19, TOX release was highly detectable in association with disease severity, contributing to lung fibroproliferative acute respiratory distress syndrome (ARDS)." (PMID 38900789, 2024). "Studies focusing on COVID-19 patients have identified sustained accessibility at exhaustion-related genes (e.g., TOX, Basic Leucine Zipper ATF-Like Transcription Factor (BATF)) and reduced accessibility at effector loci, even in convalescent phases." (PMID 41235245, 2025). "Known markers of CD4+ T cell activation (T-bet, Ki-67, CD69, TOX, and PD1) were significantly increased in baseline COVID-19 patients compared to HD." (PMID 35012610, 2022). "Known markers of CD8+ T cell activation (T-bet, Ki-67, CD69, TOX, and GZMB) were significantly increased in baseline COVID-19 patients compared to HD, supporting our hypothesis that SARS-CoV-2 infection increases peripheral T cell activation." (PMID 35012610, 2022). "Notably, TOX has also been described as an extracellular ligand acting through the TOX–RAGE axis to amplify pulmonary inflammation, highlighting that its role in COVID-19 may extend beyond nuclear transcriptional programming." (PMID 41235245, 2025).
sarcoma (4 papers, 2020 to 2024). A usually aggressive malignant neoplasm of the soft tissue or bone. "As such, the fundamental role of TOX in modulating the immune mechanism in sarcomas needs further validation." (PMID 36005179, 2022). "Notably, the key exhaustion differentiation TF TOX was expressed in most T cell subsets, indicating that these different sarcoma microenvironments induce T cell dysfunction." (PMID 39658531, 2024). "There is a need for more extensive studies on these genes, as the PTGRD2, CCR3, TOX, and HOXA10 genes are still underexplored in sarcomas." (PMID 36005179, 2022). "Moreover, TOX expression makes significant differences to the overall survival in SKCM (skin cutaneous melanoma) and the disease‐free survival in SARC (sarcoma)." (PMID 32700817, 2020).
angioimmunoblastic T-cell lymphoma (3 papers, 2020 to 2022). A mature T-cell non-Hodgkin lymphoma, characterized by systemic disease and a polymorphous infiltrate involving lymph nodes and extranodal sites. "We found that the majority of precursor B/T lymphoblastic, follicular and diffuse large B-cell lymphomas, nodular lymphocyte-predominant Hodgkin lymphomas and angioimmunoblastic T-cell lymphomas strongly expressed the TOX protein." (PMID 32106280, 2020).
chronic lymphocytic leukemia (3 papers, 2020 to 2025). "There was no or only rare TOX expression in chronic lymphocytic leukemia (CLL), classical Hodgkin lymphoma, and myeloma." (PMID 33743809, 2021).
colorectal cancer (3 papers, 2021 to 2023). A primary or metastatic malignant neoplasm that affects the colon or rectum. "Similar to the present study, bioinformatics analysis demonstrated that TOX expression is negatively correlated with TumorPurity and positively correlated with ImmuneScore and StromalScore in colorectal cancer." (PMID 36726491, 2023). "Abnormal TOX expression is found not only in T-ALL but also in solid tumors (colorectal cancer (CRC), breast cancer, and lung adenocarcinoma)." (PMID 36969216, 2023). "As colorectal cancer progresses toward metastasis, TOX expression decreases." (PMID 36969216, 2023).
diffuse large B-cell lymphoma (3 papers, 2016 to 2020). "In 4/10 patients with a BCL6+ primary cutaneous diffuse large B-cell lymphoma, leg type (PCDLBCL,LT) and in 2/2 patients with a secondary cutaneous BCL6+ diffuse large B-cell lymphoma (DLBCL), TOX was expressed by more than 50 % of the neoplastic B-cells." (PMID 27180090, 2016).
lung squamous cell carcinoma (3 papers, 2020 to 2023). "In lung squamous cell carcinoma, C1QC induced CD8+ T cell exhaustion by up-regulating the immunosuppressive TOX pathway genes, reducing OS." (PMID 36992705, 2023).
Obesity (3 papers, 2016 to 2024). Accumulation of substantial excess body fat. "SNP rs7842858 is located on TOX, which has been reported to be associated with obesity and diabetes." (PMID 27701450, 2016). "Moreover, additional immune checkpoints, such as TIM-3, LAG-3, TIGIT, and EB4, and exhaustion markers, such as TOX, TCF-7, and Eomes, were not increased on CD8 T cells in obesity, suggesting that obesity does not accelerate classical T cell exhaustion." (PMID 35103755, 2022).